BMPR1A (bone morphogenetic protein receptor type 1A)
Diseases named in the same sentence as BMPR1A in open-access papers (continued):
Sharing a sentence is not in itself a finding about the gene and the disease.
atrioventricular septal defect (2 papers, 2019 to 2022). "Heterozygous missense variants in BMPR1A have been reported in association with atrioventricular septal defects." (PMID 31493347, 2019). "Enrichment of heterozygous rare or novel BMPR1A missense variants in a population of patients with atrioventricular septal defects (3 out of 81 patients) provides further evidence of the role of BMPR1A in cardiac formation." (PMID 31493347, 2019). "Populations with atrioventricular septal defects are enriched for rare missense BMPR1A variants." (PMID 31493347, 2019).
bladder cancer (2 papers, 2016 to 2019). "To further confirm the requirement for Hh/BMP signaling feedback in the subtype determination of human bladder cancer, we performed xenograft transplantation of a human bladder cancer cell line that was engineered to express shRNA targeting SHH or BMPR1A." (PMID 31036156, 2019).
Fanconi Anaemia (2 papers, 2020 to 2022). "These include variants in genes encoding FANCE, a subunit of the Fanconi Anaemia (FA) nuclear complex; NKX2-1, a transcription factor and negative regulator of the NF-κB signalling pathway; and other recognized oncogenes JAK2, PRDM16, BMPR1A and tumor-suppressor genes KMT2C, FAT4, and LRP1B." (PMID 35954343, 2022).
gastrointestinal polyp (2 papers, 2023 to 2025). A polypoid tumor that arises from any part of the gastrointestinal tract and protrudes into the lumen. "This also indicates that SMAD4 and BMPR1A should be included in the panel of genes analyzed in all patients suspected to suffer from a genetic predisposition to intestinal polyposis." (PMID 37354305, 2023). "None of the six proven or obligatory BMPR1A variant carriers with gastrointestinal polyps or cancer from families FCCX-U/V had hamartomatous polyps." (PMID 41023686, 2025).
hamartoma (2 papers, 2015 to 2023). A benign and excessive tumor-like growth of mature cells and normal tissues which grow in a disorganized pattern. "Some genes are involved in the pathogenesis of hamartoma development, including SMAD4, PTEN, STK1, and BMPR1A." (PMID 36923765, 2023).
juvenile polyposis of infancy (2 papers, 2021 to 2023). Juvenile polyposis of infancy (JPI) is the most severe form of juvenile gastrointestinal polyposis and is characterized by pancolonic hamartomatous polyposis from stomach to rectum, diagnosed in the first two years of life. "Combined loss of PTEN and BMPR1A has a synergistic effect, resulting in juvenile polyposis of infancy (JPI), a very severe hereditary polyposis syndrome." (PMID 33822054, 2021). "Juvenile polyposis of infancy (JPI) is caused by microdeletions in chromosome 10 that result in haploinsufficiency of two tumor suppressor genes: phosphatase and tensin homolog deleted on chromosome 10 (PTEN) and bone morphogenetic protein receptor type IA (BMPR1A)." (PMID 33822054, 2021).
liposarcoma (2 papers, 2016 to 2021). A usually painless malignant tumor that arises from adipose tissue. "For the first time, we identify high BMP2 expression within the context of high BMPR1A expression as a biomarker of disease relapse in dedifferentiated liposarcomas." (PMID 27114889, 2016). "Thus, it appears that the detrimental effects of BMPR1A biased BMP2 expression are confined to the context of soft tissue sarcomas and in particular dedifferentiated liposarcomas." (PMID 27114889, 2016). "Further to linking BMPR1A-biased BMP2 expression to reduced disease free survival, we report a detailed differential expression analysis in both the sarcoma dataset as a whole and dedifferentiated liposarcomas." (PMID 27114889, 2016).
lymph node metastasis (2 papers, 2013 to 2021). "Furthermore, BMPR1A, BMPR1B, and BMPR2 were associated with clinical factors, including age, ethnicity, tumor size, and lymph node metastasis." (PMID 34036102, 2021). "Multivariate Cox regression survival analysis indicated that tumor maximum diameter of 20 mm or more, lymph-node metastasis, and invasion to surrounding tissue, followed by BDNF-positive expression or BMPR1A-negative expression were the most significant predictors of short DSS." (PMID 23531103, 2013).
prostate tumor (2 papers, 2014 to 2020). "We show that BMPR1a in myeloid cells plays a pro-tumorigenic role in prostate tumor growth, and that loss of BMPR1a impairs tumor progression." (PMID 32318332, 2020). "This suggests that BMPR1a deletion in prostate tumor macrophages may inhibit the growth of tumors in vivo." (PMID 32318332, 2020). "Additional factors including Bmpr1a might be required for the induction of prostatic tumors." (PMID 24731097, 2014). "However, there are no reports on Bmpr1a function in prostatic tumor by mouse genetic studies." (PMID 24731097, 2014).
pulmonary arterial hypertension (2 papers, 2015 to 2025). "BMPR1A and SMAD1 in our gene set are two core components in BMP pathway, which has shown to be related to pulmonary arterial hypertension and vascular calcification." (PMID 25958224, 2015).
Rectal prolapse (2 papers, 2023). Protrusion of the rectal mucous membrane through the anus. "Those with contiguous deletion of PTEN and BMPR1a can present with JPS of infancy, with a severe phenotype of GI bleeding, diarrhoea, exudative enteropathy and rectal prolapse." (PMID 37400896, 2023). "In addition to large deletions of BMPR1a being identified in patients with JPS, cases of JPI have been observed in patients with contiguous deletion of PTEN and BMPR1a, which often presents in the first two years of life with severe GI bleeding, diarrhoea, exudative enteropathy and rectal prolapse." (PMID 37400896, 2023).
renal carcinoma (2 papers, 2021 to 2022). A carcinoma arising from the epithelium of the renal parenchyma or the renal pelvis. "Furthermore, in primary and metastatic RCC clinical samples, we showed that LAPTM5 negatively correlated with BMPR1A levels and predicted lung metastatic frequency in renal cancer." (PMID 35842443, 2022). "MiR-196a promotes renal cancer cell migration by directly targeting Bram1 and inhibits Smad1/5/8 phosphorylation and MAPK pathways through BMPR1A and EGFR." (PMID 34803496, 2021).
adenovirus infection (1 paper, 2012). "To determine whether BMP signaling is involved in the wound healing response in liver injury, we induced CCl4 liver injury in Bmpr1a-KO mice generated by single injection of Ad-Cre for 14 days when inflammatory response by adenovirus infection should be cured." (PMID 22701178, 2012).
Arrhythmia (1 paper, 2018). Any cardiac rhythm other than the normal sinus rhythm. "Two genes associated with potential polyposis syndromes (SMAD4, BMPR1A) and KCNJ2, associated with arrhythmia phenotypes, were included in the list of genes considered actionable among pediatric populations." (PMID 29301385, 2018).
breast tumours (1 paper, 2023). "ACVR1C, TGFBR2, TGFBR3, ACVR2A, ACVR1, BMPR1A and BMPR2 were lower in breast tumours while ACVR1B and BMPR1B exhibited relatively higher expression levels in paired tumours compared with normal breast tissues, in the TCGA_BRCA cohort." (PMID 37333824, 2023).
chondromalacia (1 paper, 2012). Pathological processes involving the chondral tissue (cartilage). "Since localizations of chondromalacia (CM) has previously been described as a critical factor for long-term prognosis following treatment of cartilage defects, this parameter was evaluated in this study with regard to a possible different expression of BMPR-1A and BMP-2." (PMID 22272175, 2012).
chronic cholecystitis (1 paper, 2013). "Therefore, we found in the current study that positivity rates of were significantly higher for BDNF and significantly lower for BMPR1A in gallbladder adenocarcinoma compared with peritumoral adenomatous polyp, and chronic cholecystitis tissues." (PMID 23531103, 2013). "In addition, the BDNF positivity and BMPR1A negativity in peritumoral tissues, polyps, and chronic cholecystitis epithelium was accompanied by moderate or severe dysplasia." (PMID 23531103, 2013).
Cirrhosis (1 paper, 2012). A chronic disorder of the liver in which liver tissue becomes scarred and is partially replaced by regenerative nodules and fibrotic tissue resulting in loss of liver function. "BMP2, BMPR1A, FGF7, FGFR2 and ID3 were more highly expressed in cirrhosis than HCC, while the BMP inhibitors were more highly expressed in tumors." (PMID 23667740, 2012).
coloboma (1 paper, 2018). An abnormality in which a part of a structure in one or both eyes is missing. "Exome sequencing of superior coloboma patients identified rare variants in a Bone Morphogenetic Protein (Bmp) receptor (BMPR1A) and T-box transcription factor (TBX2)." (PMID 29522511, 2018).
colorectal adenoma (1 paper, 2025). An adenoma that arises from the colon or rectum. "One such event was found: a colorectal adenoma from FCCX-U (individual X.8) revealed a six-nucleotide deletion (c.334-2_337delAGGATT) affecting the splice acceptor of BMPR1A exon 4 and having a variant allele frequency of 21%." (PMID 41023686, 2025).
COVID-19 (1 paper, 2023). A disease caused by infection with severe acute respiratory syndrome coronavirus 2. "Conversely, the BMP and TGFβ signaling pathways showed specific down-regulation in endothelial cells from COVID-19 hearts, including down-regulation of BMPR1A, BMPR1B, SMAD6, and BMP6." (PMID 37830426, 2023).
developmental delays (1 paper, 2019). "We report a patient with a homozygous missense variant in BMPR1A with skeletal findings, cartilaginous airway defects, cardiac anomalies, facial dysmorphisms, and developmental delays." (PMID 31493347, 2019).
epistaxis (1 paper, 2023). Bleeding from the nose. "Most patients with SMAD4-related JPS had HHT-manifestations including epistaxis, telangiectasias and AV-malformations (mainly pulmonary), this was not noted in patients with PV in BMPR1A and/or PTEN." (PMID 37354305, 2023).
fibroids (1 paper, 2023). "Immunostained endometrium from patients with fibroids showed reduced expression of BMPR-1A, -1B, and -2." (PMID 37108180, 2023).
fibrous dysplasia (1 paper, 2012). A genetic, non-inheritable disorder caused by osteoblastic differentiation defects that result in the replacement of bone marrow and trabecular bone by fibrous stroma and immature bone. "Fibrous dysplasia and non-fibrous dysplasia subjects could be clearly separated by differences in the expression of BMP2, BMP4, BMPR1A, BMPR2, and other members of the BMP pathway." (PMID 23230423, 2012).
gall bladder carcinoma (1 paper, 2013). "In the current study, increased expression of BDNF and decreased expression of BMPR1A were associated with increased risk of metastasis, regional invasion, and mortality in gall bladder carcinoma." (PMID 23531103, 2013).
gallbladder adenocarcinoma (1 paper, 2013). A carcinoma that arises from glandular epithelial cells of the gall bladder. "In the current study, we found that increased expression of BDNF or decreased expression of BMPR1A were independent predictors of poor DSS rates in gallbladder adenocarcinoma." (PMID 23531103, 2013). "In the current study, we found that BMPR1A levels were lower in gallbladder adenocarcinoma compared with benign samples." (PMID 23531103, 2013). "Similarly, multivariate Cox regression analysis showed increased expression of BDNF or decreased expression of BMPR1A are independent predictors of poor DSS rates in gallbladder adenocarcinoma." (PMID 23531103, 2013).
gallbladder cancer (1 paper, 2013). "The current study indicated that decreased expression of BMPR1A contributes to metastasis and poor prognosis in gallbladder cancer." (PMID 23531103, 2013). "More extensive studies are required to determine the mechanistic roles of BDNF and BMPR1A in the development and progression of gallbladder cancer." (PMID 23531103, 2013). "We suggest that there may be a relationship between BDNF and BMPR1A, but it remains unclear how BDNF and BMPR1A together affect the action of tumors, such as gallbladder cancer." (PMID 23531103, 2013). "However, the expression levels of BDNF and BMPR1A and their clinicopathologic significance in malignant tumors, particularly gallbladder cancer, have not been thoroughly evaluated." (PMID 23531103, 2013).
granulosa cell tumor (1 paper, 2016). A slow-growing, malignant tumor, characterize by the presence of granulosa-like cells and Call-Exner bodies, that is almost always found in the ovary. "The expression of Gli genes that encode transcription factor effectors of sonic hedgehog signaling is also upregulated in the granulosa cell tumors of Bmpr1a/Bmpr1b conditional knockout mice." (PMID 27344183, 2016).
hepatic disease (1 paper, 2012). "Liver-specific knockout of the Bmpr1a gene after Ad-Cre infection is a very useful tool for elucidating the important role of BMP signaling in the wound healing response, and for the development of therapeutic protocols for hepatic disease based on the mechanism of the healing process." (PMID 22701178, 2012).
Hydrocephalus (1 paper, 2019). Hydrocephalus is an active distension of the ventricular system of the brain resulting from inadequate passage of CSF from its point of production within the cerebral ventricles to its point of absorption into the systemic circulation. "Conditional knockout of the Bmpr1a gene alone using the Bcre-32 transgene results in a viable mutant with a limb phenotype and hydrocephalus; we have not observed any neuroanatomical differences in the hindbrain of this single mutant." (PMID 31869353, 2019).
hyperthyroidism (1 paper, 2024). Overactivity of the thyroid gland resulting in overproduction of thyroid hormone and increased metabolic rate. "In this study, we observed increased expression of Slc2a4 in osteoblasts with hyperthyroidism in vitro indicating possibly elevated glucose uptake due to higher energy demands in thyroid hormone-stimulated osteoblasts, an effect that was blocked in Bmpr1a-deficient cells." (PMID 38719881, 2024). "Given that loss of Bmpr1a expression in osteoclasts did not prevent hyperthyroidism-driven bone loss, we next focused on osteoblasts." (PMID 38719881, 2024). "Comparison of the bone phenotypes of hyperthyroid versus euthyroid bone cell-specific conditional knockout mice suggests that the osteoblastic, but not osteoclast, BMP receptor BMPR1A is a main driver of hyperthyroidism-associated bone disease." (PMID 38719881, 2024). "Thus, we identified the osteoblastic BMP receptor Bmpr1a as a critical contributor to hyperthyroidism-driven high bone resorption in male and female mice." (PMID 38719881, 2024). "In bone tissue of Bmpr1afl/fl;Osx-Cre mice, Bmpr1a expression tended to decrease in mice with active Cre-recombinase (−59.4%, P = 0.07) and Klf9 expression was upregulated by 78.4% with hyperthyroidism as compared with Cre-negative, euthyroid mice." (PMID 38719881, 2024).
meningioma (1 paper, 2024). A generally slow growing tumor attached to the dura mater. "Our study of the inhibitory concentration of K02288 suggested that inhibition of BMPR1A occurred, and since GREM2 also inhibits BMPR1A, so we conclude that BMPR1A-mediated signals are responsible for the growth, cellular senescence, and calcification of meningiomas." (PMID 38446374, 2024). "Primary cultured meningioma cells showed very characteristic morphology and expressed the BMP receptor (BMPR1A)." (PMID 38446374, 2024).
microtia (1 paper, 2024). "To understand the molecular mechanisms underlying the development of microtia, we examined the signaling pathways altered by Bmpr1a deficiency in auricle samples." (PMID 38690987, 2024).
nephrotoxicity (1 paper, 2017). Toxicity that causes injury to the kidney or damages its function. "Also, BMPR1A, SMAD7, SMURF1 have been reported to be related to kidney fibrosis which is one key indicator of kidney nephrotoxicity." (PMID 28414804, 2017).
oesophageal cancer (1 paper, 2023). "Pancreatic and oesophageal cancer were seen in patients with pathogenic BMPR1A variants." (PMID 37354305, 2023).
oral squamous cell carcinoma (1 paper, 2020). "This phenomenon may be linked to malignant progression given that overexpression of BMPR1A has been implicated in the malignant transformation of oral squamous cell carcinoma." (PMID 32708289, 2020).
osteosarcoma (1 paper, 2016). A usually aggressive malignant bone-forming mesenchymal neoplasm, predominantly affecting adolescents and young adults. "The osteosarcoma cell line U-2 OS showed highest expression of BMPR1A by IHC, which was echoed in RNAseq data from three sarcoma cell lines, where BMPR1A expression far exceeded that of BMPR1B." (PMID 27114889, 2016).
osteosclerosis (1 paper, 2021). Abnormally high bone density. "As previous studies have shown that Bmpr1a deletion increases preosteoblast proliferation as a main cause for osteosclerosis, we set out to determine whether Wnt7b has a similar effect by performing EdU labeling experiments." (PMID 34031510, 2021).
Parkinson disease (1 paper, 2012). A progressive degenerative disorder of the central nervous system characterized by loss of dopamine producing neurons in the substantia nigra and the presence of Lewy bodies in the substantia nigra and locus coeruleus. "Several of them include genes known to be involved in causing genetic diseases in humans, such as the locus involved in Parkinson's disease (region Ger3, Park2), or juvenile polyopsis (region Ger2, Bmpr1a)." (PMID 22956910, 2012).
sarcoma (1 paper, 2016). A usually aggressive malignant neoplasm of the soft tissue or bone. "By stratifying the 263 samples represented in the TCGA sarcoma dataset based on the ratio of BMPR1A to BMPR1B mRNA, we were able to define two clear groups." (PMID 27114889, 2016). "Similarly, we find that sarcoma patients with BMPR1A biased BMP2 expression have significantly reduced disease free survival." (PMID 27114889, 2016). "It is tempting to speculate that increased turnover of extracellular matrix in sarcomas is at least in part mediated by BMPR1A and this contributes to the observed poor prognosis of patients with BMPR1A-biased signalling." (PMID 27114889, 2016). "To discount prognostic influences of BMPR1A, BMPR1B or BMP2 expression individually, we constructed Kaplan-Myer curves for the entire sarcoma dataset and compared patients with the highest and lowest 10% expression of BMPR1A, BMPR1B, BMPR2, BMP2 and BMP7." (PMID 27114889, 2016). "We reasoned that as BMPR1A expression is enriched relative to BMPR1B in sarcoma cell lines, BMP2-BMPR1A signalling may be important in progression of this tumour type." (PMID 27114889, 2016). "Although this trend is present in the sarcoma dataset as a whole, we did not observe prognostic ability of BMPR1A signalling in four other solid tumours." (PMID 27114889, 2016).
seminoma (1 paper, 2015). A radiosensitive malignant germ cell tumor found in the testis (especially undescended), and extragonadal sites (anterior mediastinum and pineal gland). "In CIS, seminomas and ECs, expression of BMP8B, BMPR1A /2, SMAD1 /4 and ID1 /2 was detected, while ID3 expression was restricted to ECs." (PMID 26226633, 2015).
sirenomelia (1 paper, 2012). Sirenomelia is a rare, genetic, developmental defect during embryogenesis disorder characterized by fusion of the lower limbs and associated with some degree of lower extremity reduction and persistent vitelline artery. "Also, it has been shown that the removal of the BMP receptor 1a (Bmpr1a), specifically from the interlimb mesoderm with the Isl1Cre line, leads to the approximation of both hindlimbs, but it does not to sirenomelia." (PMID 23028704, 2012).